MIR3180-2 (microRNA 3180-2)
Synonyms: hsa-mir-3180-2; mir-3180-2
Gene: MicroRNA gene on chromosome 16 (16,309,879 to 16,309,966, forward strand). Ensembl gene ENSG00000265373.
Gene Ontology:
Biological process: miRNA-mediated post-transcriptional gene silencing